SF3B1 (splicing factor 3b subunit 1)
Diseases named in the same sentence as SF3B1 in open-access papers (continued):
Sharing a sentence is not in itself a finding about the gene and the disease.
anemia (38 papers, 2012 to 2025). A reduction in the number of red blood cells, the amount of hemoglobin, and/or the volume of packed red blood cells. "Commonly, SF3B1 mutations are found in a form of MDS known as refractory anaemia with ring sideroblasts and refractory cytopenia with multilineage dysplasia." (PMID 40485569, 2025). "This was formally classified by the WHO in 2022 as a distinct entity, due to homogeneity within SF3B1‐mutated patients with erythroid dysplasia, ring sideroblasts, severe anemia, and a relatively good prognosis." (PMID 40124717, 2025). "CMML and MDS with RS/SF3B1 mutation differ in many clinical features but share others, such as anemia." (PMID 39011475, 2024). "We observed SF3B1 mutations in 10 cases (6%), with these patients showing a higher rate of transfusion-dependent anemia and reduced survival, similar to that observed in patients included in the chromatin/spliceosome category." (PMID 37568719, 2023). "From a morphological point of view, in the presence of mutated SF3B1, the evidence of anemia, optionally associated with erythroid dysplasia in the bone marrow, definitely supports the diagnosis of MDS/MPN-T." (PMID 37370785, 2023). "Mutations across all biological pathways were more frequent in high-risk patients except for SF3B1 mutation, which is associated with refractory anemia with ring sideroblasts and appeared in the low risk group." (PMID 37274292, 2023). "Mutations in SF3B1 occur largely in refractory anemia with ringed sideroblasts, and the overwhelming majority of such cases with SF3B1 mutants have a favorable clinical prognosis with a low risk of transformation to AML." (PMID 32727068, 2020). "Mice conditionally expressing K700E mutation (Mx1-Cre Sf3b1+/K700E) develop progressive macrocytic anemia, inefficient cellular differentiation, and failure in bone marrow reconstitution capacity." (PMID 31766606, 2019). "Our finding that SF3B1 knockdown significantly impairs human erythropoiesis demonstrates the critical role of SF3B1 in normal human erythropoiesis and implies the contribution of SF3B1deficiency to the anemia of MDS patients with SF3B1 mutation." (PMID 29433555, 2018). "The significantly impaired growth of SF3B1-knockdown erythroid cells strongly suggests that deficiency of SF3B1 can lead to anemia." (PMID 29433555, 2018). "Mutated SF3B1 gene is highly enriched in patients with refractory anemia with ringed sideroblasts, and rarely detected in MDS-RAEB patients." (PMID 28108816, 2017). "Thus, the resulting decreased levels of MAP3K7 transcripts are responsible for p38/MAPK deactivation and greater and faster downregulation of GATA1, ultimately leading to apoptotic erythroid cell death and anaemia in MDS patients with SF3B1 K700E mutation." (PMID 40485569, 2025). "Blood count analysis showed equal proportions of leukocytes across the mutational spectrum of the MDS cohort but indicated increased ring sideroblasts (RS) and anemia specifically in SF3B1-mutated MDS, which is consistent with the current WHO consensus classification of MDS-RS45,46." (PMID 41253811, 2025). "Accordingly, in a retrospective study that we conducted, we found that patients with PMF and secondary MF harboring the SF3B1 mutation had anemia and a high transfusion burden, in line with the impaired erythroid differentiation and anemia noted in SF3B1-mutated patients with MDS." (PMID 37444441, 2023). "It has been shown that MDS patients with SF3B1 mutation are characterized by isolated anemia." (PMID 29433555, 2018). "Our results propose that the anemia associated with mutant SF3B1 may be a consequence of globally disrupted splicing rather than effects on particular genes while other features of SF3B1-mutant MDS may be gene-specific." (PMID 27604819, 2017). "We excluded patients with anemia alone, which may lead to a lower SF3B1 mutation in the MDS cohort." (PMID 37087521, 2023).
anemia (continued). "MDS/MPN with thrombocytosis and SF3B1 mutation (MDS/MPN-T-SF3B1) is defined as thrombocytosis (platelets > 450,000 × 109/L) with anemia with minimal blasts (<1% in PB and <5% in BM)." (PMID 37568631, 2023). "Luspatercept is well tolerated and effective in the treatment of anemia in low-risk MDS and is approved for the treatment of transfusion-dependent low-risk MDS patients with RS and/or SF3B1 mutations." (PMID 37007111, 2023). "This study explains the mechanism by which severe anemia occurs in SF3B1 mutant MDS patients and identifies a direct role for MAP3K7 in the proper regulation of erythroid differentiation, leading to further prevention of anemia." (PMID 37007111, 2023). "SF3B1 mutant MDS is closely associated with RS morphology and is characterized by ineffective erythropoiesis, often resulting in severe anemia." (PMID 37007111, 2023). "Sf3b1+/K700ETet2−/− mice showed similar characteristics to the ones we report here, such as anemia, expansion of the LT-HSC compartment, and erythroid and megakaryocyte dysplasia." (PMID 36030305, 2022). "Double mutant mice generated by the breeding of Sf3b1+/K700E and Tet2 knock-out mice manifested a more severe anemia compared to mice with a sole alteration in Sf3b1 or Tet2." (PMID 31766606, 2019). "Despite these marked differences, Sf3b1K700E/+ mice did go on to develop progressive anemia, a central feature of SF3B1-mutant MDS." (PMID 27604819, 2017). "In the absence of SF3B1, anemia must be associated with erythroid-lineage dysplasia and ring sideroblasts to support the diagnosis of MDS/MPN-RS-T, NOS." (PMID 37370785, 2023). "One study, which retrospectively evaluated luspatercept in MDS-RS patients in routine clinical practice, found limited value in securing durable anemia responses, while a single institution case series demonstrated potential clinical benefit in patients with LR-MDS with RS and SF3B1 mutation." (PMID 36517487, 2022). "We also evaluated genes associated with mitochondrial function (Abcb7, Alas2, and Sod2), which may possibly explain the anemia phenotype in Sf3b1+/− mice." (PMID 25481243, 2014). "SF3B1 mutations have been associated with a good impact on overall survival and disease progression to AML in large series of patients, including a majority of refractory anemia with RS (RARS)." (PMID 23327988, 2012). "In our cohort, only five patients with the SF3B1 mutation showed no anemia." (PMID 40342275, 2025). "Overall, these findings support that SF3B1 mutations in MDS may lead to erythroid defects such as erythrocyte apoptosis, erythrocyte cycle arrest, and delayed erythrocyte differentiation, explaining the clinical features of anemia seen more frequently in MDS patients." (PMID 37007111, 2023). "However, it is not clear whether deficiency of SF3B1 directly contributes to the anemia of the patients." (PMID 29433555, 2018). "Indeed, in recent years, expanding treatment options in MDS have included some important novel therapies for anaemia in RS-MDS, like luspatercept, which has proven to be more effective than EPO in LR-MDS patients and those affected by SF3B1-mutant MDS." (PMID 38672645, 2024). "Sf3b1+/− mice also show an excess of ring sideroblasts in the bone marrow, without features of anemia, while the homozygous knockdown of Sf3b1 is lethal in embryos." (PMID 23327988, 2012).
Thrombocytosis (34 papers, 2014 to 2026). Increased numbers of platelets in the peripheral blood. "In the International Consensus Classification (ICC), however, assignment to the category MDS/MPN with thrombocytosis and SF3B1 mutation can be made as the presence of ring sideroblasts is regarded as “common but no longer required” for diagnosis." (PMID 40844204, 2026). "The differential diagnosis of AMKL mainly lies in histopathology, encompassing MDS 5q-, RARST (now MDS/MPN with SF3B1 mutation and thrombocytosis), panmyelofibrosis, and myeloproliferative tumors (including evolving cases)." (PMID 40547921, 2025). "Specific subtypes of MDN/MPN can be associated with thrombocytosis, specifically MDS/MPN with SF3B1 mutation and thrombocytosis and MDS/MPN NOS (unclassifiable)." (PMID 40104156, 2025). "According to the fifth edition of the WHO classification, MDS/MPN-RS-T, now classified as MDS/MPN with SF3B1 mutation and thrombocytosis (MDS/MPN-T-SF3B1), has the most favorable prognosis among all MDS/MPN types." (PMID 39337700, 2024). "MDS/MPN-RS-T had its nomenclature recently updated in the 2022 WHO classification to MDS/MPN with SF3B1 mutation and thrombocytosis." (PMID 38139212, 2023). "For example, it is known now in MDS/MPN with ring sideroblasts and thrombocytosis (MDS/MPN-RS-T) that the JAK2 V617F mutation drives the thrombocytosis while the SF3B1 mutation drives the increased ring sideroblasts." (PMID 36810551, 2023). "MDS/MPN with ring sideroblasts and thrombocytosis is redefined based on SF3B1 mutation and renamed MDS/MPN with SF3B1 mutation and thrombocytosis." (PMID 35732831, 2022). "MDS/MPN with ring sideroblasts and thrombocytosis have been redefined in the 2022 WHO classification based on SF3B1 mutation and renamed MDS/MPN with SF3B1 mutation and thrombocytosis." (PMID 36140729, 2022). "It is interesting to note that macrocytic anemia which is characterized by giant cells is frequently present in MDS subtype with increased ring sideroblasts and thrombocytosis with SF3B1 mutations." (PMID 35478057, 2022). "MDS/MPN with ring sideroblasts and thrombocytosis (MDS/MPN‐RS‐T) most commonly involves spliceosome mutations (namely SF3B1) and mutations in the JAK‐STAT pathway." (PMID 35844680, 2021). "Among SF3B1-mutated patients, the acquisition of a myeloproliferative phenotype (often characterized by progressive thrombocytosis) has been induced by the simultaneous presence of JAK/STAT pathway mutations." (PMID 34440317, 2021). "Regarding myelodysplastic/myeloproliferative neoplasms, MDS/MPN with ring sideroblasts and thrombocytosis (formerly refractory anemia with ring sideroblasts associated with marked thrombocytosis [RARS-T]) was frequently associated with SF3B1 mutations." (PMID 32784800, 2020). "In some instances, splicing factor (SF) mutations have provided diagnostic utility and information on clinical outcomes as exemplified by SF3B1 mutations associated with increased ring sideroblasts (RS) in MDS-RS or MDS/MPN-RS with thrombocytosis." (PMID 31766606, 2019). "The disease features demonstrated did not meet the World Health Organization (WHO) criteria for myelodysplastic/myeloproliferative neoplasm (MDS/MPN) with SF3B1 mutation and thrombocytosis as the presence of at least 15% ring sideroblasts is regarded as an essential diagnostic criterion." (PMID 40844204, 2026). "In this cohort, there were also five patients with the diagnosis of MDS with del5q, who harbored SF3B1 mutation, and 14 patients with MDS/MPN with RS and thrombocytosis." (PMID 39944234, 2025). "The SF3B1 mutation correlated strongly with ring sideroblasts in the bone marrow, and the presence of SF3B1/JAK2 mutations along with ring sideroblasts and thrombocytosis can be used to establish the diagnosis of MDS/MPN-RS-T." (PMID 39337700, 2024). "In this entity, it was found that the SF3B1 mutation drives the formation of ring sideroblasts and that the JAK2 V617F mutation drives the thrombocytosis." (PMID 36810551, 2023).
Thrombocytosis (continued). "Conversely, this entity is separated from SF3B1 mutated MDS/MPN forms in the ICC and designed as “MDS/MPN with sideroblasts and thrombocytosis, NOS”." (PMID 37370785, 2023). "According to the WHO 2022 classification, the term MDS/MPN with ring sideroblasts and thrombocytosis has been kept as an acceptable term to be used for cases with wild-type SF3B1 and ≥15% ring sideroblasts." (PMID 37370785, 2023). "The term MDS/MPN with ring sideroblasts and thrombocytosis has been retained as an acceptable term to be used for cases with wild-type SF3B1 and ≥15% ring sideroblasts." (PMID 35732831, 2022). "SF3B1 mutations are disease-defining in MDS/MPN with RS and thrombocytosis (MDS/MPN-RS-T) and are seen in about 5% of chronic myelomonocytic leukemia (CMML), without a well-established association with leukemic transformation and overall survival." (PMID 36671709, 2022). "Based on SF3B1 status, the fifth WHO renamed MDS/MPN with RS as MDS/MPN with SF3B1 mutation and thrombocytosis, while MDS/MPN with RS and thrombocytosis is used for cases with wild-type SF3B1 and ≥15% RS." (PMID 36230848, 2022). "This overlap syndrome is characterized by frequent mutations in SF3B1 (90%), that strongly correlate with BM ring sideroblasts, and mutations in JAK2 (40%) that correlate with thrombocytosis." (PMID 33925681, 2021). "The combination of JAK2 V617F and SF3B1 mutations is associated with MDS/MPN with ring sideroblasts and thrombocytosis." (PMID 30573779, 2019). "The Sf3b1+/− mice demonstrated macrocytic anemia, thrombocytosis, dyserythropoiesis, RS and EMH in the spleen." (PMID 25481243, 2014). "The WHO-HAEM4R entity “MDS/MPN with ring sideroblasts and thrombocytosis” (MDS/MPN-RT-T) has been largely redefined based on the highly prevalent SF3B1 mutation in these cases, and is renamed “MDS/MPN with SF3B1 mutation and thrombocytosis” in both WHO-HAEM5 and ICC." (PMID 39075565, 2024). "Both classifications now expand on these categories; in particular, MDS/MPN with ring sideroblasts and thrombocytosis (MDS/MPN-RS-T) has been split into two entities in the ICC 2022 based on the presence/absence of the SF3B1 mutation." (PMID 37370785, 2023). "Somatic SF3B1 mutations are strong associated to MDS patients with ring sideroblasts with/without thrombocytosis suggesting, a causal relationship between SF3B1 mutation and formation of ring sideroblasts." (PMID 34440317, 2021). "However, “MDS/MPN with ring sideroblasts and thrombocytosis” has been retained as a repository for cases with wild-type SF3B1 and ≥15% ring sideroblasts in both ICC and WHO-HAEM5, as the clinical behavior and biologic features of these infrequent cases is uncertain." (PMID 39075565, 2024). "The information about the mutational status of SF3B1 has not only allowed the redefinition of the diagnostic criteria in MDS but also the improvement of the risk stratification, identifying new sub-categories: MDS-SF3B1 and MDS/MPN with SF3B1 mutation and thrombocytosis." (PMID 36230848, 2022). "Co-expression of SF3B1 with DNMT3A, TET2 or ASXL1 promotes myelodysplasia with ring sideroblasts, while acquisition of JAK2 mutations, and less frequently MPL (4%) and SH2B3 (4%) mutations, constitute secondary events that promote thrombocytosis and contribute to the myeloproliferative phenotype." (PMID 33925681, 2021). "Among the CH mutations, genes encoding Additional sex combs like 1 (ASXL1), Splicing factor 3B subunit 1 (SF3B1), DNA methyltransferase 3a (DNMT3A), Src homology 2 B3 (SH2B3, also named LNK), and JAK2 are considered to be associated with thrombocytosis and/or platelet hyper-reactivity." (PMID 34502524, 2021). "Sf3b1+/− exhibited macrocytic anemia (MCV: 49.5 ± 1.6 vs 47.2 ± 1.4; Hgb: 5.5 ± 1.7 vs 7.2 ± 1.0) and thrombocytosis (PLTs: 911.4 ± 212.1 vs 878.4 ± 240.9) compared to Sf3b1+/+ mice." (PMID 25481243, 2014).
chronic myelomonocytic leukemia (24 papers, 2019 to 2025). A myelodysplastic/myeloproliferative neoplasm which is characterized by persistent monocytosis, absence of a Philadelphia chromosome and BCR/ABL fusion gene, fewer than 20 percent blasts in the bone marrow and blood, myelodysplasia, and absence of PDGFRA or PDGFRB rearrangement. "SF3B1 mutations are relatively uncommon in chronic myelomonocytic leukemia (CMML) patients, occurring in about 5–6% of cases, and similar to MDS, these mutations are associated with the RS phenotype." (PMID 40729294, 2024). "SF3B1 mutations are strongly associated with ring sideroblasts, and SRSF2 mutations are detected in MDS and about half of cases of chronic myelomonocytic leukemia (CMML)." (PMID 37610626, 2023). "Notably, SF3B1 mutations are associated with MDS with ringed sideroblasts (MDS-RS), while SRSF2 mutations are linked to chronic myelomonocytic leukemia (CMML)." (PMID 39941875, 2025). "Finally, for comparison, in the analysed articles, around 33% of chronic myelomonocytic leukemia (CMML) patients harbored SRSF2 mutations; 8% U2AF1 mutations, 9% ZRSR2 mutations and 5%, SF3B1 mutations." (PMID 32784800, 2020). "Mutations in SF3B1, SRSF2, and U2AF1 have been associated with specific disease subtypes with SF3B1 being mostly mutated in MDS-RS, SRSF2 occurring mostly in chronic myelomonocytic leukemia (CMML), and U2AF1 in secondary AML." (PMID 31766606, 2019).
myeloproliferative neoplasm (24 papers, 2014 to 2026). A clonal hematopoietic stem cell disorder, characterized by proliferation in the bone marrow of one or more of the myeloid (i.e., granulocytic, erythroid, megakaryocytic, and mast cell) lineages. "In contrast to MDSs, SF3B1 mutations in myeloproliferative neoplasms (MPNs) seem to elevate the risk of fibrotic transformation." (PMID 40729294, 2024). "Elevated CDK13 expression has been reported in myelodysplastic/myeloproliferative neoplasm with ring sideroblasts and thrombocytosis (MDS/MPN-RS-T), in which 80–90% of patients harbor SF3B1 mutations, a splicing factor regulated by CDK12/13." (PMID 41491919, 2026). "In the realm of CMML, there is another subtype of MDS/(MPN) myeloproliferative neoplasms overlap disease, namely a small group of CMML patients presenting with ring sideroblasts and/or SF3B1 mutation." (PMID 40556336, 2025). "SF3B1 mutations are frequent in patients with refractory anemia with ringed sideroblasts (RARS), with myelodysplastic/myeloproliferative neoplasms with ringed sideroblasts and thrombocytosis (RARS-T), and also in up to 14% PMF patients." (PMID 37284191, 2023). "In myelodysplastic/myeloproliferative neoplasm with ring sideroblasts and thrombocytosis (MDS/MPN-RS-T), SF3B1 mutations are pesent in 70-90% of cases." (PMID 30251956, 2019). "In contrast, the presence of JAK2, CALR, or MPL mutations in the absence of SF3B1 should orient the diagnosis to a myeloproliferative disorder." (PMID 37370785, 2023).